ALB (albumin)
Diseases named in the same sentence as ALB in open-access papers (continued):
Sharing a sentence is not in itself a finding about the gene and the disease.
anemia (continued). "Furthermore, as determined in our new prognostic model, anemia or decreased albumin level was considered a risk factor." (PMID 36924334, 2023). "Additionally, in rheumatic patients, high levels of interleukin-1β were associated with anaemia, neutrophilia, lymphopenia, low albumin levels, and increased CRP, which are elements partly used in several of the inflammation-scores." (PMID 35027001, 2022). "The laboratory tests revealed anemia, iron deficiency, eosinophilia, slightly elevated serum level of total IgE and severe hypoproteinemia, with enteral protein loss (α1AT = 1,800 μg/g) requiring human albumin administration." (PMID 35174199, 2022). "However, differences were observed according to age, FPG, or anemia in the association between serum albumin levels and HbA1c." (PMID 34055818, 2021). "Multivariate analysis showed that age (p = 0.013), BMI (p = 0.001), weight loss (p = 0.001), anemia (p = 0.005), pre-albumin (p = 0.010), albumin (p = 0.002), tumor location (p = 0.001), tumor size (p = 0.002), and NIH classification (p = 0.001) were risk factors for nutritional status." (PMID 34778339, 2021). "We also measured comorbidities (CCI), dependence, nutritional status (BMI, albumin), nursing home residents, and dementia as factors other than age, but age was the only factor that showed a significant association with anemia recognition by multivariate logistic regression." (PMID 34769698, 2021). "Results demonstrated that increases in concentrations of albumin were directly associated with recovery from anemia (aOR: 2.67, 95% CI:1.05–6.75, p = 0.04) whereas increases in total proteins were directly associated with persistent anemia (aOR: 0.44, 95% CI: 0.24–0.78, p = 0.01)." (PMID 33072136, 2020). "Multiple regression analysis revealed that the progression of G category was a significant risk factor for anemia; other risk factors included female sex, low serum albumin level, narrower difference between sodium and chloride concentrations, and high serum CRP level." (PMID 32687544, 2020). "Initial laboratory tests indicated iron deficiency anemia and an albuminemic state with low hemoglobin (Hb) (73 g/L), total protein (51.1 g/L), albumin (27.5 g/L), prealbumin (39 mg/L), serum iron (2.3 umol/L) and total iron binding capacity (35.44 umol/L) level." (PMID 32410331, 2020). "However, in these previous studies, anaemia, low haemoglobin and low albumin were also reported to be associated with a higher risk of DR, DKD and cardiovascular disease, and smoking and high platelet count are well-known risk factors." (PMID 31427625, 2019). "Results on lower hemoglobin and albumin may point to a higher risk of anemia among the unemployed immigrant population." (PMID 31548886, 2019). "Anemia and serum albumin in patients with ESRD have been associated with cognitive impairment." (PMID 29633885, 2018). "High mGPS, high serum IL-8, and low serum albumin, particularly, associated with normocytic anemia." (PMID 29348549, 2018). "It has been suggested that the findings are specific to the unique population with a high incidence of malaria (57%), severe anaemia <5 g/dl (32%) and acidosis (base deficit >8 mmol/l, 51%) with saline and albumin causing disease-specific deterioration and worsening of both anaemia and acidosis." (PMID 28050897, 2017). "In addition to body weight loss and composition, blood measurements include only albumin, anemia, CRP, and absolute lymphocyte number; together with a questionnaire containing two questions related with PHP, two related with ANO and 11 related with QoL." (PMID 28261113, 2017). "In Korea, Choi and colleagues conducted a prospective study to examine the clinical characteristics of anemia in older Koreans and reported that the independent risk factors included an older age, a low BMI, a low albumin level, a higher creatinine level, and the female gender." (PMID 27812118, 2016).
anemia (continued). "The first axis was associated with anemia, inflammation, and low levels of calcium and albumin." (PMID 25761112, 2015). "In men, low serum albumin was also associated with higher anaemia prevalence." (PMID 24586229, 2014). "Anemia and too high hemoglobin concentrations might lead to adverse clinical outcome, and age, albumin and creatinine are significantly associated with anemia." (PMID 21600038, 2011). "However, multivariate Logistic regression analysis confirmed that only albumin levels was the risk factors of anemia." (PMID 20959070, 2010). "Low serum albumin levels may indicate inflammation and malnutrition, whereas cholesterol, hemoglobin, and platelet levels are linked to atherosclerosis, anemia, and bleeding or thrombotic risks—all highly prognostic for cardiovascular outcomes in dialysis patients." (PMID 41351012, 2025). "Hence, we posit a close association between albumin levels and anemia occurrence." (PMID 39621534, 2024). "However, we also know that COVID-19 could cause anemia and that albumin level decreases in severe inflammation, meaning that they can also be markers of a more severe disease, with increased risk of persistent kidney damage." (PMID 34640618, 2021). "This experiment aims to investigate the alleviating effect of donkey serum albumin on CP-induced anemia." (PMID 42064839, 2026). "We observed that the albumin concentration was the lowest in the severe anemia group, and highest in the mild anemia group." (PMID 41550749, 2026). "CKD (adjusted OR 2.11, 95% CI 1.32-3.38), lower eGFR, lower albumin, and higher BNP were independently associated with anemia, whereas sodium-glucose cotransporter-2 inhibitor use was associated with lower odds." (PMID 42051733, 2026). "Additional studies, including hemoglobin, albumin, renal and hepatic function, and hemoglobin electrophoresis, were normal, ruling out anemia and hemoglobinopathies." (PMID 41837234, 2026). "Greater FPE severity corresponded with elevated blood pressure, proteinuria, and anemia, alongside decreased estimated glomerular filtration rate (eGFR) and albumin levels." (PMID 42159291, 2026). "These patients were typically in a more debilitated condition preoperatively, often with anemia, low preoperative albumin (requiring nutritional optimization), and previous exposure to two or more biologics." (PMID 41538669, 2026). "Stratification into quartiles revealed that patients with lower albumin, higher UARs, and lower ACRs were older, had more comorbidities, poorer nutritional status, and a higher prevalence of concomitant anemia." (PMID 41452958, 2026). "Cluster 2 was a younger group characterized by anemia and lower serum albumin and total cholesterol levels." (PMID 40542100, 2025). "demonstrates that effectively managing glycemia and anemia in diabetic patients leads to reductions in blood pressure, urine albumin secretion, and pulse rate." (PMID 39968673, 2025). "Patients in the CCU group had significantly lower and below the reference range haematological indices: red blood cells (RBC), haemoglobin (HB) and haematocrit (HCT), suggesting anaemia, as well as albumin (ALB) and fT3." (PMID 41286140, 2025). "Higher ALB level, female, ABCB1 rs1045642, MTHFR rs1801131, and MTHFD1 rs2236225 were associated with lower risk of anemia, while the combination of furosemide, torasemide, bumetanide, and levetiracetam associating with higher risk." (PMID 40832604, 2025). "Out of the patients who had normal bone marrow at baseline, 2 patients developed mild anemia, 3 patients experienced a mild decrease in white blood cell count, and 2 patients experienced a mild reduction in albumin levels after treatment." (PMID 40094004, 2025). "Serum albumin levels, skeletal muscle mass, anemia status, metabolic parameters, protein-bound uremic toxins, and QoL scores were comparable between the two groups." (PMID 40806006, 2025).
anemia (continued). "In our setting, open abdomen can close secondary as long as there is adequate control of infections and other factors that impair wound healing like low albumin levels and anemia." (PMID 40171449, 2025). "Regular monitoring of haemoglobin levels, waist circumference, and albumin levels in women, along with comprehensive reproductive health services, will help alleviate anemia and improve overall health outcomes." (PMID 40063574, 2025). "The study identified several factors significantly associated with WD, including male gender, emergency surgery, low serum albumin levels (<3.5 g/dL), anemia (hemoglobin <10 g/dL), and wound contamination." (PMID 39748882, 2025). "In CD, lower age at the diagnosis and lower albumin level correlated with anemia severity (p = 0.0007 and <0.0001, respectively)." (PMID 40165528, 2025). "In contrast, younger patients (≤30 years) generally presented with milder disease, characterized by the least severe lung involvement, mildest anemia, and highest albumin levels." (PMID 40095487, 2025). "Independent risk factors for anemia include diabetic nephropathy, CKD stages, body mass index, smoking, leukocyte count, serum albumin, iron markers, and calcium and phosphorus concentrations." (PMID 40802782, 2025). "For example, a patient aged < 60-years (0-points), with ISS stage III (73.5-points), ECOG score < 2 (0-points), anemia (72.0-points), neutropenia (79.5-points), and albumin levels ≥ 35 g/L would have a total score of 290.5 points." (PMID 41232431, 2025). "Patients who developed hypophosphatemia during hospitalization were older, exhibited poorer nutritional status, had more comorbidities, lower albumin levels, worse renal function, more severe anemia, and elevated ferritin levels." (PMID 40183914, 2025). "Specifically, E. faecalis monocolonization led to a higher colitis-related disease activity (DAI score), reduced anemia, increased fecal albumin levels, and trends towards lowered fecal calprotectin compared to GF mice receiving DSS alone." (PMID 41472066, 2025). "Serum albumin (p =.008), blood iron (p <.001), number of erythrocytes (p <.001), and the hematocrit value (p <.001) were also significantly lower in patients with anemia." (PMID 40836330, 2025). "Human Albumin was injected to correct hyperproteinaemia, and Polysaccharide Iron Complex for anaemia." (PMID 40308961, 2025). "Predictors of postoperative cholangitis were preoperative perforation, preoperative cholangitis, type 4A, removal drainage, anemia, level of serum albumin and amylase." (PMID 41230442, 2025). "Patients in the anemia groups exhibited significantly lower serum iron and ferritin levels, serum albumin values, and prognostic nutritional index (PNI) and were older." (PMID 40046524, 2025). "As for clinical variables, PROMIS-SP CAT T-scores were significantly lower among participants with more comorbidities, anemia, low serum albumin, and low eGFR." (PMID 40814629, 2025). "Abnormal abdominal ultrasound findings were associated with pCALs and should be assessed at diagnosis, particularly in boys with an incomplete clinical presentation, anemia, and low albumin levels." (PMID 40447734, 2025). "The presence of thrombocytopenia in NDMM patients significantly correlated with invasive clinical manifestations, including high myeloma burden, severe anemia, low albumin levels, renal failure, and elevated β2‐MG and LDH levels." (PMID 41176718, 2025). "Incomplete response to first-line therapy was more common in patients with adverse clinical features, including stage III/IV, ECOG performance status > 1, elevated LDH, anemia, multiple extranodal sites involvement, and low albumin." (PMID 41156312, 2025). "PC 4 correlated with clinical biomarkers associated with general inflammatory processes (SR and blood albumin levels), anaemia (haemoglobin, erythrocyte volume fraction and erythrocyte count) and kidney function (creatinine)." (PMID 40046342, 2025).
anemia (continued). "In DSS-treated mice, monocolonization was associated with modest and mixed effects, including a higher colitis-related disease activity score, reduced anemia, increased fecal albumin and a trend towards reduced fecal calprotectin." (PMID 41472066, 2025). "In multivariable logistic regression analysis, factors significantly associated with severe anaemia were female sex (Adjusted Odds Ratio (AOR: 14.3, 95% CI: 2.14–126.6), albumin (AOR: 0.93 95% CI: 0.88–0.98) and creatinine levels (AOR: 1.01 95% CI: 1.00-1.03)." (PMID 39901231, 2025). "Young patients exhibited mild disease with the least severe lung involvement, mild anemia, and highest albumin levels." (PMID 40095487, 2025). "In conclusion, age, ISS stage, ECOG score, anemia, neutropenia, and albumin levels are influencing factors for pulmonary infections during chemotherapy in MM patients." (PMID 41232431, 2025). "Normochromic normocytic anemia; Leucopenia; Albumin = 2.6 gm/dl; Mild elevation of transaminases; ESR = 115 mm; serum ferritin level = less than 2000 μg/ dl." (PMID 40104478, 2025). "The prominent abnormalities considered target parameters for diagnosing FIP include anemia, increased serum protein levels (especially characterized by higher globulin and lower albumin), a reduced albumin-to-globulin (A: G) ratio, and hyperbilirubinemia." (PMID 41360910, 2025). "This immunonutritional marker is derived from the integration of parameters reflecting immune status (lymphocyte and platelet counts), nutritional status (albumin), and anemia status (hemoglobin)." (PMID 40686698, 2025). "Laboratory tests indicated mild anemia (hemoglobin 110 g/L), increased erythrocyte sedimentation rate (24 mm/h), normal white blood cell counts and classifications, and slightly lowered albumin (39.2 g/L)." (PMID 40313643, 2025). "Frail patients had a significantly higher prevalence of preoperative anemia and lower albumin levels, creatinine clearance, and Mini-Cog scores than prefrail and robust patients." (PMID 41272515, 2025). "Laboratory tests revealed elevated white blood cell and neutrophil counts, anemia, thrombocytopenia, elevated glucose and HbA1c levels, decreased serum protein and albumin levels, renal failure, coagulopathy, and bacteriuria." (PMID 40901238, 2025). "Studies on the relationship between anemia and the C-reactive protein–albumin–lymphocyte (CALLY) index, a novel inflammatory measure, are scarce." (PMID 41204576, 2025). "Key lab findings included albumin <35 g/l, anemia with hemoglobin <10 g/l, elevated β2-MG >5.5 mg/l, reduced estimated glomerular filtration rate (eGFR) <60 ml/min/1,73 m2, and elevated serum phosphate (PO43-) >1.45 mmol/l, all tied to a higher SI risk." (PMID 40013147, 2025). "The blood biochemistry and routine blood test showed normal, except for anemia [102g/L (normal: 115–150g/L)], increased globulin[63g/L(20-35g/L)] and decreased albumin[30.6g/L (40-55g/L)]." (PMID 41357603, 2025). "Laboratory tests on admission (day 1) revealed elevated white blood cell and neutrophil counts, anemia, thrombocytopenia, elevated glucose and HbA1c levels, decreased serum protein and albumin levels, renal failure, coagulopathy, and bacteriuria." (PMID 40901238, 2025). "A complete assessment and laboratory workup revealed normocytic normochromic anemia and severe malnutrition (albumin: 2.5 g/dL)." (PMID 41556010, 2025). "In the model, the factors influencing the score in descending order were age, neutropenia, ISS stage, anemia, albumin levels, and ECOG score." (PMID 41232431, 2025). "D-dimer/albumin captures hypercoagulability and inflammation; immobility and central venous catheters are established clinical risk factors; and elevated CRP, anemia, and thrombocytosis reflect pro-thrombotic states in cancer." (PMID 41156207, 2025). "Significant differences were observed between the two groups in terms of age, ISS stage, ECOG score, anemia, neutropenia, and albumin levels (p < 0.05)." (PMID 41232431, 2025).
anemia (continued). "In summary, CRP, albumin, and lymphocytes are important and interrelated elements in the occurrence and development of anemia." (PMID 41204576, 2025). "Patients with anemia with HF commonly exhibit comorbidities such as low albumin levels, cardiovascular issues, and alterations in their hemodynamic status." (PMID 39773062, 2025). "For GBM, they are elevated LDH, CD5 + expression, time to relapse > 12 m, initial response, age, ALB, B symptoms, and anemia." (PMID 40418267, 2025). "Factors associated with LOS were analyzed, including age, body mass index, operative time, clinical scores, anemia, albumin levels, age group, sex, and ASA physical status." (PMID 39845254, 2024). "Our study has successfully developed and validated a novel model for predicting the occurrence of anemia following chemotherapy in osteosarcoma patients, integrating ALB, Ca, CREA, D‐dimer, and ESR as predictive variables." (PMID 39621534, 2024). "We further performed Chi-square test and found that the following variables showed between-group differences (P < 0.05): pulmonary infection/pneumonia, low albumin, anemia, respiratory failure, renal insufficiency, and blood transfusion." (PMID 38616997, 2024). "The patient’s treatment regimen encompassed the administration of albumin over 12 hour infusions when symptomatic hypovolemia was suspected and red blood cell transfusion to address anemia, alongside antiviral therapy during the postnatal period." (PMID 38808020, 2024). "Common risk factors such as ALB, Ca, CREA, D‐dimer, and ESR were identified through the analysis of each risk prediction model, indicating their significant impact on anemia." (PMID 39621534, 2024). "In this study, patients typically displayed elevated NLR and CRP levels, decreased PAB and ALB levels, along with symptoms such as low-grade fever, malaise, and anemia." (PMID 39703501, 2024). "The likelihood of anaemia also increased markedly with lower serum albumin concentrations (AOR: 2.30 [95% CI = 2.22 to 2.37]) for every 1 g/dl lower albumin." (PMID 38092441, 2024). "Positive laboratory findings include anemia for age, thrombocytosis (>4,50,000) after the seventh day of fever, albumin <3 g/dl, elevated ALT levels, TLC >15,000/cu mm, and urine ≥ 10 pus cells/HPF." (PMID 38975482, 2024). "Laboratory indices revealed anaemia, as indicated by a haemoglobin level of 92 g/L, and hypoproteinaemia, as indicated by an albumin level of 22 g/L." (PMID 38519924, 2024). "The increasing GDF-15 level was determined by a decrease in the hepcidin level as well as by anemia and renal dysfunction, and the decreasing hepcidin level was determined by a decrease in stored iron and a decrease in serum albumin level." (PMID 38883134, 2024). "Hemoglobin and albumin, though influenced by factors like anemia and nutritional status, also reflect the degree of inflammation in AAV patients." (PMID 39459426, 2024). "Initial hematological and serological tests at our institute indicated mild anemia and a reversal of the albumin-globulin ratio." (PMID 40093349, 2024). "Laboratory indices revealed anaemia, as indicated by a haemoglobin level of 87 g/L, and hypoproteinaemia, as indicated by an albumin concentration of 15.7 g/L." (PMID 38519924, 2024). "Femoral head necrosis, ASA Physical Status > 2, osteoarthritis, total hip arthroplasty, anemia, autotransfusion, preoperative fibrinogen, and preoperative albumin had the lower average effect." (PMID 38840126, 2024). "Our findings identified 25 indicators, including Gender, Surgery, Type of surgery, LYM%, MO%, LYM, BLT, TP, ALB, SF, K, CA, CREA, UA, PT, APTT, FIB, D‐dimer, CRP, hs‐CRP, ESR, PCT, IgA, CEA, and CA‐153, as independent risk factors for anemia." (PMID 39621534, 2024). "Biochemical alterations, including anemia, inflammation, and low albumin levels, play significant roles in this process." (PMID 39685109, 2024).